SQSTM1 (sequestosome 1)
Diseases named in the same sentence as SQSTM1 in open-access papers (continued):
Sharing a sentence is not in itself a finding about the gene and the disease.
prostate carcinoma (14 papers, 2013 to 2025). A carcinoma that arises from epithelial cells of the prostate gland. "In mouse models of prostate cancer, the signalling adaptor p62/Sqstm1 is selectively inactivated in adipocytes." (PMID 39941741, 2025). "Of note, one VCP patient developed colorectal cancer during the time of follow‐up (at age 66) and 3 other patients (1 VCP, 2 SQSTM1 + TIA1) had prostate cancer." (PMID 36861178, 2023). "In the present study we found that: (i) at variance with benign lesion, prostate cancer cells underwent SQSTM1 accumulation, i.e., clearly displayed a defective autophagic process but, also, (ii) prostate cancer accumulated AMBRA1 and (iii) this increase positively correlated with the Gleason score." (PMID 26423274, 2015). "Here we investigated whether SQSTM1/p62 (p62) overexpression, as a marker of autophagic flux, was related to aggressiveness of human prostate cancer (PCa) and whether autophagy regulated the treatment response in sensitive but not resistant PCa cell lines." (PMID 24655592, 2014). "Androgen-independent prostate cancer cell lines (PC-3 and DU 145) were tested where 3-AWFA treatment lead to conversion of cytosolic MAP1LC3B-I/LC3B-I to MAP1LC3B-I/LC3B-II (microtubule-associated protein-1 light chain 3β) and reduction of the autophagy substrate, SQSTM1 (sequestosome 1)." (PMID 31731424, 2019). "Selective inactivation of the signal transduction adapter p62/Sqstm1 in adipocytes, secretion of osteopontin, and upregulation of CPT1A expression drive prostate cancer invasion." (PMID 41219902, 2025). "To investigate if hypoxia induces autophagy in prostate cancer cells, we detected LC3B and SQSTM1 expression level in LNCaP and 22Rv1 cells treated with hypoxia in the presence or absence of CQ." (PMID 25333253, 2014). "p62/SQSTM1 is stained in some carcinomas such as HCC, intestinal carcinomas, anal carcinoma, and prostate carcinoma." (PMID 24086340, 2013). "Conversely, in LNCaP cells, ALA increased p62/SQSTM1 expression, most likely because in this prostate cancer cell line ALA does not affect the Nrf2/KEAP1/p62/SQSTM1 axis or the oxidative/redox balance system." (PMID 38069431, 2023). "The data reported in this pilot study demonstrated an increased expression of AMBRA1 and SQSTM1, which were also associated with an accumulation of LC3II in prostate cancer but not in benign lesion." (PMID 26423274, 2015). "Accordingly, in the case of AMBRA1 we detected a good correlation with the Gleason score, whereas the SQSTM1 expression levels, previously suggested as not altered in PCa, seem to not correlate with prostate cancer grading system." (PMID 26423274, 2015). "Additionally, the elevation of HDAC6 induced by P62 (also known as sequestosome-1, SQSTM1) promotes the epithelial-mesenchymal transition (EMT) process and impairs autophagic flux, facilitating the growth, migration and invasion of prostate cancer cells." (PMID 31901237, 2020).
liver cancer (13 papers, 2018 to 2024). An epithelial or non-epithelial malignant neoplasm that arises from the liver. "HK2 is prone to be recognized by the autophagy receptor protein SQSTM1/p62 for autophagic degradation after K33-linked polyubiquitination by the E3 ligase TRAF6 in liver cancer." (PMID 35006464, 2021). "The interaction among PRKCI and SQSTM1 coordinates the oxidative metabolic reaction in hepatic neoplasm." (PMID 39015499, 2024). "The interaction between PRKCI and SQSTM1 regulates autophagy, thus playing a role in liver cancer development." (PMID 39015499, 2024). "USP14 regulates the autophagy function of liver cancer cells by regulating the interaction between SQSTM1/P62 and HK2." (PMID 38383348, 2024). "SQSTM1 was reported to inhibit hepatic stellate cell activity, fibrosis, and liver cancer by binding to the vitamin D receptor." (PMID 36795724, 2023). "Together, these analyses of various datasets reveal that SQSTM1/p62 is significantly upregulated at both transcriptional and translational levels in liver cancer patients." (PMID 35814476, 2022). "High SQSTM1 levels continuously activate Nrf2 and its downstream target genes, which independently promote growth of liver cancer cells during the early stages of the disease." (PMID 34484469, 2021). "Recently, Duran and colleagues found that the vitamin D receptor inhibits liver cancer as well as fibrosis through a process involving p62/SQSTM1 ligation of the VDR." (PMID 29659559, 2018). "SQSTM1 accumulation leads to chronic inflammation in liver cancer." (PMID 34830108, 2021). "Accordingly, a recent study implied that p62/SQSTM1 is highly phosphorylated at serine 349 in the tumor tissues of HCV-positive HCC patients and that phosphorylated p62/SQSTM1 drives the glucoronate and glutathione synthesis pathways to enhance drug resistance and malignancy of liver cancer." (PMID 30544615, 2018). "Furthermore, we investigated whether sh-USP14 inhibits the AKT and SQSTM1 signaling pathways in liver cancer cells by regulating HK2." (PMID 38383348, 2024). "The results revealed that the expression of HSP90AA1, PPIA, SQSTM1, and USP21 was significantly increased in liver cancer tissues compared with normal liver tissues (p < 0.05), which was consistent with the results of the bioinformatics analysis." (PMID 36795724, 2023). "Additionally, accumulated p62/SQSTM1 and defected cathepsin D were positively related to the liver tissues of people with chronic HBV infection and HBV-associated liver cancer, suggesting that HBV’s inhibition of autophagy could result in the development of HCC." (PMID 30642133, 2019). "In liver cancer cells, ferroptosis activators (e.g., erastin, sorafenib) could enhance the expression of SQSTM1/p62 (sequestosome 1), a competitive inhibitor of KEAP1 (Kelch-like ECH-associated protein 1)." (PMID 32103754, 2020).
Obesity (13 papers, 2015 to 2025). Accumulation of substantial excess body fat. "Here we tested a novel approach to treat obesity: by weekly intramuscular administration of the plasmid (DNA vaccine) encoding p62 (SQSTM1) protein." (PMID 28915571, 2017). "SQSTM1 has been implicated in a number of diseases including neurodegenerative diseases, cancer, obesity, and insulin resistance." (PMID 25325195, 2015). "Finally, six genes (Sec61a1, Insr, Sirt1, Pdpk1, Sin3a, and Sqstm1) were predicted to be associated with diabetes and obesity." (PMID 32257911, 2019). "p62/Sqstm1-knockout mice are a model of metabolic syndrome; show obesity, insulin resistance, and non-alcoholic fatty liver (NAFL); and develop non-alcoholic steatohepatitis (NASH) in response to the feeding of a high-fat diet (HFD)." (PMID 36439272, 2022). "PLIN1, an essential protein for lipid storage and lipolysis, can be ubiquitinated and then degraded through SQSTM1-mediated autophagy under obesity-related inflammatory states." (PMID 30741926, 2019). "Here, we show that SQSTM1 can be transcriptionally upregulated by obesity-related inflammatory stimuli in mature adipocytes, which indicated autophagy activity might be underestimated in obese conditions when SQSTM1 was used as an autophagy substrate." (PMID 30741926, 2019). "In mice, the knock out of SQSTM1 led to obesity and impaired glucose tolerance." (PMID 29467647, 2018). "The results showed the significant accumulation of SQSTM1/p62 and LC3B after the induction of obesity-related SAP, suggesting impaired autophagic flux." (PMID 40806352, 2025).
ovarian carcinoma (13 papers, 2017 to 2025). A malignant neoplasm originating from the surface ovarian epithelium. "A study of the molecular bases of aberrant autophagy in ovarian cancer which was found to be associated with an enhanced expression of the selective autophagy receptor SQSTM1/p62 has led to the identification of RPN11/PSMD14 as a negative regulator of autophagy levels." (PMID 39430244, 2024). "PSMD14 inhibits autophagy and thus influences the progression of ovarian cancer through the LRPPRC/Beclin1-Bcl-2/SQSTM1 signaling pathway." (PMID 40182048, 2025). "The Beclin1-Bcl-2/SQSTM1 signaling pathway inhibits autophagy and thus affects ovarian cancer progression." (PMID 40182048, 2025). "SHH and SQSTM1 were found to be highly expressed in the samples of borderline ovarian tumors, and even higher in epithelial ovarian cancer (EOC), compared with those of benign ovarian tumors." (PMID 34076346, 2021). "We detected the expressions of SHH and SQSTM1 in borderline ovarian tumor tissues, epithelial ovarian cancer (EOC) tissues and benign ovarian tumor tissues." (PMID 34076346, 2021). "In contrast, RHEB and SQSTM1, known negative regulators of autophagy, showed decreased expression in resistant samples, indicating a strong correlation between autophagy activation and the development of cisplatin resistance in ovarian cancer." (PMID 41502518, 2025). "In ovarian cancer, SQSTM1 is involved in mechanisms that confer resistance to chemotherapy." (PMID 39941813, 2025). "We found up‐regulation of SHH and accumulation of SQSTM1/P62 in epithelial ovarian cancer." (PMID 34076346, 2021). "Finally, we explored whether factors such as ATF4, GPX4, GSS, KEAP1, NFE2 like BZIP transcription factor 2 (NEF2L2), SLC7A11, SQSTM1, ATG3, ATG4D, and ATG5 have potential as non-invasive diagnostic markers for ovarian cancer." (PMID 37215446, 2023). "The results of cDNA expression profile analysis indicated that six genes, including GPX4, GSS, KEAP1, SQSTM1, SLC7A11, ATG3, and ATG5, were highly expressed in tumor tissues from patients with ovarian cancer." (PMID 37215446, 2023). "In our study, the significant upregulation of SHH and SQSTM1 was observed in borderline and EOC, suggesting the activation of SHH signaling and inhibition of autophagy in ovarian cancer." (PMID 34076346, 2021). "Analogously, cisplatin-resistant ovarian cancer SKOV3 cells expressed more p62/SQSTM1 and were resensitised upon knockdown of p62/SQSTM1." (PMID 28767070, 2017). "In addition, in ovarian cancer tissue samples, the expression levels of GPX4 and SQSTM1 were about 8-fold higher than those of the other genes." (PMID 37215446, 2023). "Following HULC siRNA transfection of ovarian cancer cells, ATG7, LC3 and LAMP1 mRNA and protein expression both were significantly higher than in the control, whereas expression of SQSTM1 and ITGB1 was significantly decreased by HULC siRNA transfection compared with the negative control (P<0.05)." (PMID 29022892, 2017). "In the ovarian carcinoma SKOV3 cells, inhibition of LSD1, using the S2101 inhibitor, activated autophagy by decreasing the phosphorylation of AKT, MTOR, and P70S6K and led to a decrease in P62/SQSTM1 and LC3B-II levels, as well as the number of LC3B-positive vesicles." (PMID 31861179, 2019). "Therefore, we suggest that the lncRNA HULC may cause changes in cell homeostasis by inhibiting autophagy and promoting ovarian cancer by regulating ATG7, LC3, LAMP1 and SQSTM1 expression." (PMID 29022892, 2017).
distal myopathy (12 papers, 2018 to 2024). Distal myopathy refers to a group of muscle diseases which share the clinical pattern of predominant weakness and atrophy beginning in the feet and/or hands. "A myopathy-associated mutation in SQSTM1 (c.116511G>A) was initially described in a family with a dominantly inherited distal myopathy and one singleton case with a sporadic distal myopathy, both with rimmed vacuolar pathology." (PMID 39501809, 2024). "Welander distal myopathy results from a missense change in the prion-like domain of TIA1, whereas a variant affecting a nearby amino acid residue leads to an identical distal myopathy phenotype in combination with SQSTM1 mutations." (PMID 33974137, 2021). "The recently reported digenic distal myopathy caused by a SQSTM1 mutation and a variant in the PrD protein TIA1 further demonstrates how a combined effect of variants in PQC and client proteins together can determine the phenotypic outcome." (PMID 32093037, 2020). "While TIA1- and SQSTM1/TIA1-associated distal myopathy display a rather identical clinical phenotype compared to MATR3 (in terms of onset, muscle weakness and histopathology), none of these disease entities typically include a relevant dysphagia and dysphonia." (PMID 32361838, 2020). "We present the first detailed clinical and pathologic data from three unrelated families with predominant distal myopathy associated with a known pathologic variant in SQSTM1 (p.Pro392Leu) and a variant in TIA1 (p.Asn357Ser)." (PMID 29599744, 2018). "Genetic modifiers likely play a role, such as the synergistic effect of TIA1 (c.1070A > G, p.Asn357Ser) and SQSTM1 mutations affecting the UBA domain, resulting in distal myopathy." (PMID 36861178, 2023). "Coexisting SQSTM1 and TIA1 variants are linked to MRV, presenting as late-onset distal myopathy; some cases are accompanied by cognitive impairment, dyspnea, and cardiac conduction abnormality." (PMID 36998782, 2023). "In previous SQSTM1-related distal myopathy reports, the tibialis anterior was always predominantly involved and completely replaced by fatty tissue on muscle MRI; in this case, it was well-preserved." (PMID 36998782, 2023). "A separate variant with a low population frequency is not pathogenic on its own but can modify the phenotype of SQSTM1 variants to present as a distal myopathy and is identified in a disproportionate number of distal myopathy cases." (PMID 38891822, 2024). "Furthermore, respective changes were not present in MR-studies from patients with MYOT- and SQSTM1/TIA1-associated distal myopathy overseen in the neuromuscular research centre in Halle." (PMID 32361838, 2020). "In keeping with this hypothesis a N357S genetic variant of TIA1 gene (encoding for a key component of cytosolic stress granules) has been shown to interact with SQSTM1 mutations to cause distal myopathy, whereas both SQSTM1 mutation and the N357S genetic variant alone do not cause myopathy." (PMID 36035996, 2022). "In contrast, relevant similarities were observed in 6 distal myopathies (TIA1, late-stage TTN, MYOT, SQSTM1/TIA1, KLHL9, ADSSL1)." (PMID 32361838, 2020). "Additionally, gluteal and paraspinal changes as observed in MATR3-myopathy were not seen in whole-body examination of a patient with SQSTM1/TIA1-associated distal myopathy, a distal myopathy that displays similar lower limb findings as compared to MATR3-associated myopathy." (PMID 32361838, 2020).
atherosclerosis (10 papers, 2018 to 2025). A disease characterized by the build-up of fatty material and calcium deposition in the arterial wall resulting in partial or complete occlusion of the arterial lumen. "Unsupervised DEGs analysis of SMCs revealed increased expression in Abcb8ECKO of TGF-β-pathway genes such as Tgfb1, Tgfb2, Tgfb3, Mmp2 and Col1a1, inflammatory genes such as Ccl2 (encoding for MCP1) and Csf1 as well as atherosclerosis-associated genes including Egr1, Sqstm1, Irf1, Sox4 and Xylt1." (PMID 41252867, 2025). "Another significant pathway is the fluid shear stress and atherosclerosis and ubiquinone pathway, which includes sequestosome-1, which is also involved in necroptosis pathway (p = 0.0321), NAD(P)H dehydrogenase [quinone] 1, and heme oxygenase." (PMID 36673375, 2023). "The data suggest that fucoidan can inhibit NLRP3 inflammasome activation by enhancing p62/SQSTM1-dependent selective autophagy to alleviate atherosclerosis." (PMID 33505579, 2020). "The present study is the first evidence that fucoidan inhibits NLRP3 inflammasome activation by enhancing p62/SQSTM1-dependent selective autophagy to alleviate atherosclerosis." (PMID 33505579, 2020). "The classical markers of autophagy, including LC3-II, p62/SQSTM1, and Beclin-1, have been identified by immunoblot and immunofluorescence microscopy analysis in both human atheroma lesions and in ApoE-null mice that spontaneously develop atherosclerosis." (PMID 30249977, 2018). "Under stress, protein aggregates are cleared by autophagic mechanisms involving ubiquitination of SQSTM1/p62 and LC3 activation, both of which play important roles in cardiac diseases, including AMI, atherosclerosis, and HF." (PMID 40948766, 2025). "For example, to alleviate atherosclerosis, fucoidan (a polysaccharide mainly composed of fucose and sulfate) inhibits NLRP3 activation through SQSTM1/p62-dependent selective autophagy." (PMID 36671400, 2022).
colon carcinoma (10 papers, 2014 to 2024). "Results showed that the deficiency of TNFR2 on MC38 and CT26 colon cancer cells markedly decreased p62/SQSTM1 expression while increased the expression of Beclin1, Atg5, and LC3-II/LC3-I." (PMID 36923938, 2023). "MAP1LC3B-II and SQSTM1 dot-like staining are shown in tissues and are associated with a poor prognosis in patients with colon cancer." (PMID 30477228, 2018). "We found that the expression of was higher the autophagy marker (LC3 and SQSTM1) in ATP13A2 low colon cancer cells, but lower in ATP13A2 high colon cancer cells." (PMID 33308286, 2020). "A strong association between LC3II and p62 (SQSTM1) expression and MDC positive staining of autophagic vacuoles in colon cancer cell lines was revealed." (PMID 26802026, 2016). "In summary, we found that shikonin suppresses colon cancer cell proliferation and migration through cellular experiments and identified eight genes (CCNB3, IL-1α, CXCL8, CDKN2A, MYC, IGFBP3, SQSTM1, and GADD45G) associated with cell senescence through systematic bioinformatics analysis." (PMID 39188951, 2024). "SQSTM1 interferes with the progression of colon cancer through the activation of autophagy." (PMID 36127676, 2022). "Therefore, it is reasonable to speculate that KCNQ1OT1-mirNAs-SQSTM1 play an important role in the activation of pyroptosis in colon cancer." (PMID 36127676, 2022). "Further, among validated DEGs were those with established roles in colon cancer and CCSC (KLF6 and SQSTM1) and those with emerging roles (SPTLC2, SEC24D, and ACACA)." (PMID 34845203, 2021). "IHC staining was performed on the 99-case colon cancer cohort to explore the relationship between the expression levels of ATP13A2, LC3 and SQSTM1, the marker of autophagy." (PMID 33308286, 2020). "In the present study, the effect of KRAS/BRAF/PIK3CA oncogenic pathways on the autophagic cell properties and on main components of the autophagic machinery like p62 (SQSTM1), Beclin-1 (BECN1) and MAP1LC3 (LC3) in colon cancer cells was investigated." (PMID 26802026, 2016). "Similarly to MARCH2, the expression of SQSTM1 was higher in colon cancer tissues than non-tumor tissues." (PMID 28749466, 2017). "Therefore, SQSTM1 and MARCH2 may represent prognostic biomarkers of malignant change in colon cancer." (PMID 28749466, 2017). "Furthermore, high MARCH2 expression correlated with increased levels of SQSTM1, supporting the hypothesis that MARCH2-regulated autophagy has an important role in the development of colon cancer." (PMID 28749466, 2017). "We next examined the expression of MARCH2, SQSTM1, p-PERK, p-EIF2α and p-IRE1α in primary colon cancer tissues and adjacent non-tumor tissues." (PMID 28749466, 2017).